IL1B (interleukin 1 beta)
Diseases named in the same sentence as IL1B in open-access papers (continued):
Sharing a sentence is not in itself a finding about the gene and the disease.
colon carcinoma (continued). "In the present study, we attempted to find out whether water-soluble polysaccharide isolated from A. heterophyllus can influence the viability of human colon carcinoma cells and change pro- (IL-1β, IL-6) and anti-inflammatory (IL-10) cytokines and nitric oxide (NO) produced by them." (PMID 31947694, 2020). "Our results, showing that FV extract is able to reverse the effects of IL1β on colon cancer cells, strongly suggest that FV may play an important role in preventing the alteration of molecular processes characterizing the inflammatory microenvironment that leads to cancer and chronic diseases." (PMID 33256057, 2020). "Thus, since we observed an up to 1 to 10 ratio of differential gene expression between CA and AA colon tumors for the IL1B and IL8 genes, our future studies will explore the relationship between the cytokine secretion patterns in AA tumors as well as in colon cancer cell lines from AA patients." (PMID 32983990, 2020). "To investigate whether St-ΔpGlux/pT-ClyA inhibits colon cancer growth by promoting increased production of IL-1β, we dynamically evaluated the efficacy of S.t-ΔpGlux/pT-ClyA for colon cancer treatment by MRI and explored the cellular origin of IL-1β in colon cancer treatment." (PMID 31754923, 2019). "Moreover, there was also a decrease in levels of inflammatory cytokines TNF-α, IL-1β, IL-6, and IL-17A in the sera or colon tissues of Trim27−/− mice, which was consistent with the decreased inflammatory cell infiltrations in colon tumors of Trim27−/− mice." (PMID 30143645, 2018). "Notably, previous studies indicated that IL-1β might be a new therapeutic target against CSCs in colon cancer and oral squamous cell carcinoma." (PMID 28865486, 2017). "Thus, the parallel up-regulation of Zeb1 and Bmi1 by IL-1β suggests that IL-β-induced self-renewal of colon cancer cells may involve the Zeb1-Bmi1 pathway." (PMID 23174018, 2012). "This indicates that IL-1β may act through Zeb1 to induce EMT in colon cancer cells." (PMID 23174018, 2012). "Using a colon cancer cell line HCT-116 and primary colon cancer cells, we have found that IL-1β can promote sphere-forming capacity concomitant with up-regulated expression of stemness markers Bmi1 and nestin in colon cancer cells, suggesting that IL-1β increases the self-renewal of colon CSCs." (PMID 23174018, 2012). "Finally, treatment of cells with LY29004 completely prevented the ability of IL-1β to protect colon cancer cells from TRAIL-induced apoptosis, implying that macrophages and IL-1β protect from TRAIL induced apoptosis through GSK3β dependent stabilization of Snail." (PMID 20661477, 2010). "Although IL-1β was shown to upregulate Snail and to downregulate E-cadherin in head and neck squamous carcinoma cells, our initial analysis revealed no major changes in the expression of epithelial or mesenchymal markers in colon cancer cells exposed to macrophage-derived factors." (PMID 20661477, 2010). "IL-1β and IL-18 can activate the NF-κB and STAT3 signaling pathways, thereby promoting cell proliferation and the production of anti-apoptotic proteins in colonic tumors." (PMID 40422233, 2025). "In a mouse model, treatment of CT-26 cancer cells with A. crassicauda venom enhanced the production of anti-tumor mediators (IL-12, IL-1β, and IFN-γ) and significantly suppressed the proliferation of colon tumor cells in a previous study." (PMID 40969416, 2025). "Overexpression of S100A8/S100A9 in mouse colon cancer cells CT26.WT led to differential increases in the secretion levels of various cytokines (CXCL5, CXCL11, GM-CSF, G-CSF, IL1a, IL1b, sTNF RI, and CCL3)." (PMID 38817853, 2024). "When colon cancer was induced with AOM/DSS, the expression of inflammation-related genes such as IL-1β, IL-6, and TNF in the blood increased, and the expression of inflammatory cytokines was confirmed in the serum of mice." (PMID 38338927, 2024).
colon carcinoma (continued). "Consistent with our results, stevioside played an anti-inflammatory and immunomodulatory role in the human colon carcinoma cell line (Caco-2) by potentially suppressing lipopolysaccharide-induced pro-inflammatory cytokine TNF-α, IL-1β, and IL-6 productions." (PMID 37237936, 2023). "C3+ TeMs (M12) and C1QA+ TeMs (M10) were clustered into the same branch, resembling the IL1B+ macro and C1QC+ TAMs identified in colon cancer, respectively." (PMID 37488416, 2023). "The previous study showed that treatment of the HT-29 colon cancer cell line with a combination of TNF-α, INF-γ, and LPS has resulted in the up-regulation of pro-inflammatory enzymes (COX-2 and iNOS) and cytokines (IL-1β and TNF-α) expression." (PMID 36900505, 2023). "As previous reported, NF-κB p65, IL-1β and TNF-α, as key signaling molecules, induced the production of IL-17, which promoted the proliferation and metastasis of colon cancer." (PMID 36774343, 2023). "In addtion, the protein level of NLRP3, ASC, cleaved-caspase-1, mature IL-1β and GSDMD-N in isolated tumors significantly increased after simvastatin treatment, suggesting the induction of simvastatin on pyroptosis in colon cancer in vivo." (PMID 37974278, 2023). "Therefore, IL-1β and Zeb1 could be potential therapeutic targets for colon cancer treatment." (PMID 37176567, 2023). "The increased levels of pro-inflammatory cytokines (TNF-& IL-1β), and tumor markers (CEA, CA19.9 and AFP) matched with a decrease in apoptotic biomarkers (CD4+) in colon cancer-bearing rats are in line with other earlier research." (PMID 36294905, 2022). "The colon cancer group showed a marked increase in serum levels of CA19.9, CEA, AFP, TNF-α, IL-1β, and colon DNA-fragmentation matched with a decrease of CD4+ compared with the control group." (PMID 36294905, 2022). "LPEPS oral administration significantly down-regulated pro-inflammatory factors (IL-8, TNF-α, and IL-1β) and up-regulated anti-inflammatory factor (IL-10) levels in the serum of AOM/DSS-induced colon cancer mice." (PMID 34945611, 2021). "IL-1β produces inflammation in NSCLC cells through downregulation of miR-101 expression via the Cox2–HIF1α pathway and supports proliferation of colon tumors through the miR-181a/PTEN axis." (PMID 34220337, 2021). "A high cholesterol diet is also responsible for macrophage production of IL-1β, through NLRP3 activation, and tumor growth in azoxymethane-induced colon cancer." (PMID 32635472, 2020). "RT-qPCR was carried out to investigate the expression of IL1β, IL6 and TNFα in colon cancer cells stimulated with LPS or siHMGB1." (PMID 32514250, 2020). "Cytokines that promote colon tumor development include the tumor necrosis factor (TNF), interleukin 6 (IL-6), interleukin 1B (IL-1B), and interleukin 8 (IL-8)." (PMID 32983990, 2020). "It has been demonstrated that IL1β, a pro-inflammatory cytokine, induces COX-2 expression in colorectal cells and that COX-2 drives colon cancer progression." (PMID 33256057, 2020). "High amounts of IL-1β and IL-1α were detected in a murine adenomatous polyposis coli (APC) colon cancer model." (PMID 32635472, 2020). "IL-1β also stabilizes Snail, an EMT actor, in an NF-κB/AKT/Wnt-dependent manner in human colon cancer cells." (PMID 32635472, 2020). "In particular, IL-1β stimulated the expression of the CSC-related marker ZEB1, induced resistance to chemotherapy, and increased sphere-forming efficiency in colon cancer cells, thus supporting a role for IL-1β in promoting CSC self-renewal and EMT." (PMID 32120774, 2020). "It was shown that BC has anti-inflammatory effects reducing the IL-1β and COX-2 expression through inhibition of NF-κB signaling pathway in human colon cancer cell line HT-29." (PMID 32183497, 2020). "For the first time, we show that MMM induce MK2 phosphorylation in colon tumor cells and when added to tumors treated with MK2 inhibitor induce production of the known MK2-downstream cytokines IL-1β, IL-6, and TNF-α." (PMID 30298062, 2018).
colon carcinoma (continued). "Succinate is widely accepted as an inflammatory signal and induces interleukin-1β (IL-1β) through HIF-1α while IL-1β has been demonstrated to be elevated in colorectal cancer, oral cancer and colon cancer." (PMID 28881853, 2017). "Therefore, the higher IL-1β plasma concentrations and lower IL-10 plasma levels in obese animals found in this study may contribute to a suppression of NK cell killing activity against tumor cells and thereby the increased colon cancer incidence in obese rats." (PMID 28357137, 2017). "Elevated levels of IL-1β, IL-6, TNF-α, MCP-1 and PGE2 are therefore accepted as major prognostic indicators for the progression of colon cancer." (PMID 27507058, 2016). "Once activated, NFκB up-regulates the transcription of various proinflammatory mediators including TNF-α, IL-1β, IL-6, COX-2 and iNOS, which typically are overexpressed in colon cancer." (PMID 25763529, 2015). "We have previously shown that IL-1β, at low doses (∼30 pM), can stimulate the expression of CFTR in T84 colon carcinoma cells, through NF-κB signaling." (PMID 24901709, 2014). "For example, TNF-α and IL-1β are potent stimulators for MMP9 in astrocytes, and IL-6 induces overexpression of MMP9 in human colon carcinoma cells, and TNF-α and IL-1β also can induce activation of NF-κB." (PMID 22529521, 2012). "The effect of IL-1β and IP6 on the expression of mRNA of MMP-1, MMP-2, MMP-3, MMP-9, MMP-10, and MMP-13 and that of their tissue inhibitors TIMP-1 and TIMP-2 in colon cancer cells using real-time QRT-PCR assay was determined." (PMID 22415590, 2012). "Proinflammatory cytokine IL-1β upregulates MMP and TIMP mRNAs expression in colon cancer epithelial cells Caco-2." (PMID 22415590, 2012). "Thus, IL-1β and Zeb1 might be new therapeutic targets against colon cancer stem cells." (PMID 23174018, 2012). "C-reactive protein (CRP), albumin, IL-1α, IL-1β, IL-6, IL-8, IL-10, TNF-α, midkine, VEGF-A, VEGF-C, leptin, adiponectin, and ghrelin serum levels are studied in 126 colon cancer patients and 36 healthy subjects." (PMID 20920199, 2010). "Here we present data which establish that TRAIL responsive colon cancer cells acquire resistance to TRAIL when cultured in the presence of macrophages, and showed that macrophage-derived IL-1β was required for their anti-apoptotic activity." (PMID 20661477, 2010). "Remarkably, the presence of THP1 macrophages or treatment with IL-1β, a cytokine produced in cocultures of tumor cells and macrophages, restored the clonogenic growth of TRAIL-treated colon cancer cells." (PMID 20661477, 2010). "A more detailed picture of clonal sensitivity towards modulators of IL-6 was obtained when IL-1β, PGE2, 1,25-(OH)2D3, and 17β-E2, singly or in appropriate combinations, were added to colon carcinoma cell cultures." (PMID 18205904, 2008). "They noted an IL-1β dose dependent production of VEGF protein and mRNA expression in cultured colon cancer cell lines." (PMID 17096856, 2006). "Similarly to IL1β, PGE2 also promoted ROS production and NOX1 and COX2 expression, which were inhibited when colon cancer cells were pre-treated with SW, CW, and BF, indicating that the bean extracts also inhibited the effects of exogenous PGE2." (PMID 39125413, 2024). "IL-1β may foster CRC growth and invasion by stimulating colon cancer stem cell (CSC) self-renewal and upregulating stemness factor genes Bmi1 and Nestin." (PMID 38671854, 2024). "This interplay between IL-1β and IL-6 in colon cancer progression was corroborated by findings from GEPIA and TIMER, with similar observations in a study involving African American colon cancer patients." (PMID 38671854, 2024). "GKT significantly prevented the protein and mRNA expression of COX2 and PGE2 production induced by IL1β, indicating that NOX1 expression and activity may be crucial for the expression of inflammatory markers in colon cancer cells." (PMID 39125413, 2024).
colon carcinoma (continued). "NLRP3 and IL1B mRNA expression was quantified in 13 matched nontumoral (NT) tissues, primary colon tumor (T) tissues and liver metastasis (M) tissues." (PMID 38486106, 2024). "UdF at a concentration of 200 μg/mL significantly reduced the release of IL-1β by cancer cells after a 24 h incubation, but none of the tested extracts affected the release of IL-6 and IL-10 in human colon tumor cells." (PMID 39519642, 2024). "Furthermore, SFN displayed significant antioxidant and chemopreventive activities by inhibiting the IL-1β-induced expression of IL-6 and the subsequent MAPK/AP-1/STAT3 signaling in HT-29 colon cancer cells." (PMID 38671854, 2024). "IL1B can also enhance the signal transduction of CTLA4, and targeting the IL1B-CTLA4 axis can effectively inhibit the occurrence of metastatic and recurrent colon cancer." (PMID 36969161, 2023). "The activation of CYP1A effectively controls the pro-oxidants and oxidative stress in colon cancer cells further, suppressing the proinflammatory cytokines IL-1β and TNF-α, which favors the deactivation of malignant cell apoptosis inhibitor NF-kB in colon cancer cells." (PMID 36430918, 2022). "Furthermore, nuclear PKM2 was reported to regulate the production of TNF-α, IL-1β, MMP-2, and MMP-9 in colon cancer cells and to activate inflammasomes." (PMID 35256696, 2022). "According to the current research, administering LME to colon cancer-model rats significantly reduced their levels of AFP, CEA, and CA 19.9, as well as immune-inflammatory markers (TNF-α and IL-1β) matched with the development of apoptotic biomarker (CD4+), compared to the control group." (PMID 36294905, 2022). "IL-1β fosters the epithelial to mesenchymal transition (EMT) process and stem cell proliferation in human primary colon cancer cells and in HCT-116 cells through the zinc finger E-box-binding homeobox 1 (ZEB1) protein, which contributes to the advancement of colon tumors." (PMID 35954156, 2022). "To assess whether IL-1β promotes cell proliferation in the AA colon cancer cell lines and how this response may differ from that seen in CA cell lines, we performed an MTS assay and tested different concentrations of IL-1β for multiple time points." (PMID 36531053, 2022). "Interestingly, post-surgery levels of PFKFB3, IL1b, HSPA1B and DDIT4 in colon cancer were increased compared to control." (PMID 36733385, 2022). "Inflammatory mediators IL-1β, TNF-α, and IL-6 are increased at the early onset of colorectal cancer, and inhibiting the production of these cytokines can be an effective strategy to prevent colon cancer development." (PMID 34684488, 2021). "In a non-alcoholic fatty liver disease (NAFLD) model with colon cancer splenic xenograft, a high-fat diet induced TAM M2 polarization and substantial IL-1β and vascular endothelial growth factor (VEGF) production in an NLR family CARD containing 4 (NLRC4)-dependent manner." (PMID 32635472, 2020). "Some inflammatory factors, such as IL-1β and TNF-α, may stimulate a sustained COX-2 expression and PGE2 production in colonic tissues, promoting proliferation and invasiveness of colon cancer epithelial cells." (PMID 28676858, 2017). "Numerous studies have verified the level of IL-1β and TNF-α in human colon cancer." (PMID 23379788, 2013). "Since Zeb1, a transcription factor that mediates EMT, was up-regulated in IL-1β-induced stem cells in serum free medium, we then investigated whether IL-1β could induce EMT phenotype in colon cancer cells." (PMID 23174018, 2012). "In this study, we investigated whether IL-1β could promote stem cell and EMT phenotypes in human colon HCT-116 cells as well as in newly established primary colon cancer cells." (PMID 23174018, 2012). "In future experiments, our three EC types extracted from bovine mesentery may also be treated with immune cytokines such as IL-1β and IL-8, in addition to tumourigenic compounds such as 25-OHC to recapitulate activated ECs in the colon tumour environment." (PMID 21070649, 2010).
colon carcinoma (continued). "Interestingly, we found that both NLRP3 and IL1B mRNA levels were significantly upregulated in both primary colon tumor (T) and liver metastasis (M) tissues compared with nontumoral (NT) tissues." (PMID 38486106, 2024). "However, ablation of GSDMD in sporadic colon tumors did not result in altered IL-1α, IL-1β, and IL-18 as well as NLRP3 or ASC speck formation." (PMID 38898209, 2024). "Increased CTLA4 levels also correlate with IL-1β expression CC as IL-1β increases the signal transduction of the CTLA4; therefore, targeting the IL-1β–CTLA4 axis may help to overcome the CC immunosuppressive TIME, as seen in colon cancer." (PMID 37508372, 2023). "Additionally, by microarray analysis, several inflammatory cytokines, such as Infγ, Tnf, and Il1β were downregulated in the TME, including colon tumor cells, immune cells, fibroblasts, and other cells, in the S100a4-Cre; Ext1f/f mice compared to those in the control mice." (PMID 36809261, 2023). "However, it has been shown that the colon cancer cell line HTM-29 cannot secrete IL-6 upon IL-1β- or TNF-α-stimulation, because these cytokines do not lead to NF-κB activation here." (PMID 34671021, 2021). "To mimic a pro-oxidant and pro-inflammatory milieu, we stimulated colon cancer cells with interleukin 1β (IL1β, 10 ng/mL, 48 h) in the presence and in the absence of different concentrations of FV extract (10, 50 μg/mL), and we measured ROS levels by means of DCFH2-DA assay." (PMID 33256057, 2020). "Using S.t-ΔpGlux/pT-ClyA may simultaneously activate TLR4 and NLRP3 signaling pathways, which increase IL-1β expression and enhance inhibition of colon cancer growth without tumor recurrence." (PMID 31754923, 2019). "CD14HiHLA-DRHi cells from CD/UC surgical resection specimens may induce differentiation of naïve T cells into Th17 cells with a CD163Lo subset able to produce greater IL-1β and IL-6 after TLR stimulation, compared to macro/microscopically normal areas from colon cancer resections." (PMID 30542349, 2018). "The treatment with anti-miR-31 could no longer increase the adhesion of colon cancer cells when endothelial cells were not stimulated with IL-1β and thereby did not express E-selectin." (PMID 27926494, 2017). "We conclude from this that in human colon cancer cells, endogenous PG production, even when stimulated by IL-1β, is too low to affect IL-6 production, and that, conversely, the chemopreventive effect on colon cancer development of COX-2 inhibitors does not involve changes of IL-6 expression." (PMID 18205904, 2008). "Furthermore, IL-1β-induced EMT cells had a greater migratory capacity as compared to parental cells that had an epithelial phenotype, which could be involved in the development, spread, and recurrence of colon cancer." (PMID 37834263, 2023). "Furthermore, binding of TIA-1 to the proximal region of the 3′-UTR of COX-2 following IL-1β has also been demonstrated by electrophoretic mobility shift assay (EMSA) in renal mesangial cells and defective RNA binding of TIA-1 has been shown to promote COX-2 expression in colon cancer cells." (PMID 29555582, 2018). "PTX3 mRNA expression and protein levels were significantly induced by IL-1β and TNF-α in human and mouse fibroblasts but not in colon cancer cells." (PMID 38243273, 2024). "Nevertheless, polyI:C did not induce TNFα, IL-1β, IL10 and IL-12p40 in HCC and colon cancer cell lines tested." (PMID 28427199, 2017). "In addition, O. splanchnicus showed a significant positive correlation with MUC2, ZO-1, Claudin, and IL-10, and a significant negative correlation with colonic tumor numbers, tumor volumes, advanced colonic lesions, TNF-α, and IL-1β." (PMID 39924893, 2025). "To investigate whether IL-1β promotes self-renewal of colon cancer cells, an important feature of CSCs, we plated HCT-116 and HPCC cells at very low densities in 96-well plates containing serum-free medium with or without IL-1β." (PMID 23174018, 2012).